BID (BH3 interacting domain death agonist)
Diseases named in the same sentence as BID in open-access papers (continued):
Sharing a sentence is not in itself a finding about the gene and the disease.
pancreatic cancer (5 papers, 2021 to 2023). "As determined by RT‐qPCR, the expression pattern of BID was lower in the pancreatic cancer tissues relative to the adjacent normal tissues, and it was positively correlated with the FOXO3 expression pattern." (PMID 34363438, 2021). "Our study primarily demonstrated the ability of LINC00472 to competitively bind to miR‐23a‐3p to boost the FOXO3 expression and transcriptionally activate the BID expression for suppression of pancreatic cancer progression." (PMID 34363438, 2021). "LINC00472 could competitively bind to miR‐23a‐3p to enhance the expression of FOXO3, which consequently could promote the BID expression, thereby suppressing proliferation and promoting the apoptosis of pancreatic cancer cells." (PMID 34363438, 2021). "An existing study elicited BID as an essential regulator of cell apoptosis in pancreatic cancer." (PMID 34363438, 2021). "Therefore, we speculated that LINC00472 may regulate the expression pattern of BID through FOXO3 to subsequently manipulate the development of pancreatic cancer." (PMID 34363438, 2021). "Furthermore, we silenced LINC00472 and/or overexpressed BID in the pancreatic cancer cell BXPC3." (PMID 34363438, 2021). "In the Catalogue of Somatic Mutations in Cancer (COSMIC) database; 135/13,389 (1.0%) samples showed co-amplification of BCL2L13, BID, CRKL and MAPK1 and frequencies > 2% were found in ovarian or pancreatic carcinomas." (PMID 37443114, 2023). "In summary, the preceding results indicated that silencing of LINC00472 inhibited the expression pattern of BID through miR‐23a‐3p/FOXO3 to promote the proliferation and inhibit the apoptosis of pancreatic cancer cells." (PMID 34363438, 2021). "The study substantiated the antitumour activity of LINC00472 in pancreatic cancer and proposed a regulatory axis in which LINC00472 competitively binds to miR‐23a‐3p to enhance the FOXO3 expression and promote BID expression." (PMID 34363438, 2021). "Such regulatory axis was verified in both in vitro and in vivo settings, and our data demonstrated that LINC00472 silencing had fundamentally suppressed BID expression through miR‐23a‐3p‐mediated inhibition of FOXO3 to promote proliferation and inhibit the apoptosis of pancreatic cancer cells." (PMID 34363438, 2021). "As the critical roles of BID were identified in initiating the apoptosis of pancreatic cancer cells, we suggested that LINC00472 may up‐regulate the expression of BID through FOXO3 to induce the apoptosis of pancreatic cancer." (PMID 34363438, 2021).
Sepsis (5 papers, 2010 to 2024). Sepsis is defined as life-threatening organ dysfunction caused by a dysregulated host response to infection. "Whether apoptosis primarily has protective or harmful consequences during systemic inflammation is still unknown but CASP3, BCL2L1, FAS, and BID are all reported to be differentially expressed in human patients suffering from different stages of sepsis." (PMID 26076814, 2015). "Moreover, in experimental models of sepsis, BID knockout mice showed nearly complete protection from sepsis-induced lymphocyte apoptosis and a marked survival advantage in polymicrobial sepsis." (PMID 20626850, 2010). "Our single-cell sequencing data demonstrated that sepsis marker genes were highly elevated in CD16+ monocytes, including NAP1L1, CFD, BID, BCL2A1, MALAT1, RNH1, and LILRA5 genes." (PMID 39294473, 2024). "In patients, Weber and colleagues recently observed an extensive apoptosis of circulating lymphocytes after severe sepsis (upregulation of BIM and BID gene expression, and a downregulation of the anti-apoptotic molecules BCL-2 and BCL-XL)." (PMID 20626850, 2010).
atherosclerosis (4 papers, 2011 to 2023). A disease characterized by the build-up of fatty material and calcium deposition in the arterial wall resulting in partial or complete occlusion of the arterial lumen. "One studies have shown that after in vitro and in vivo injection of endotoxin and LPS, six candidate genes (BATF, BID, C3aR1, IL1RN, SEC61B and SLC43A3) were identified to be associated with inflammation and atherosclerosis." (PMID 36303246, 2022). "The functions of GRK3 and BID in atherosclerosis remain poorly investigated." (PMID 33460396, 2021). "The role of BID, SEC61B, SLC43A3 in atherosclerosis is not yet established." (PMID 21827714, 2011).
clear cell renal cell carcinoma (4 papers, 2021 to 2024). "Bangbei Wan et al27 also demonstrated that BID was a diagnostic biomarker in clear cell renal cell carcinoma (ccRCC)." (PMID 33837652, 2021).
Obesity (4 papers, 2017 to 2025). Accumulation of substantial excess body fat. "Thus, Fas inhibits mitochondrial fatty acid oxidation via BID, thereby contributing to the pathogenesis of obesity-associated hepatic steatosis." (PMID 28883393, 2017). "On the basis of these and other studies mentioned in this review regarding cardiolipin and respiration, it is tempting to speculate that BID regulates metabolism, obesity, and respiration by interacting with and regulating MTCH2 activity." (PMID 41306288, 2025). "Based on these and other studies on CL and respiration mentioned in this review, it is tempting to speculate that BID regulates metabolism, obesity and respiration by interacting with and regulating MTCH2 activity." (PMID 41227324, 2025). "Additionally, several studies have reported that BID plays a role in regulating obesity/metabolism." (PMID 41227324, 2025).
bladder cancer (3 papers, 2014 to 2025). "Based on this clinical foundation, we investigated the anti-tumor effects of KD01, a novel type 5 recombinant oncolytic adenovirus previously developed by our team engineered to express truncated BID (tBID), in bladder cancer." (PMID 40283946, 2025). "For example, in the bladder cancer cell line T24, CuE administered at 0.5–1 μM induced apoptosis and triggered up-regulation of Fas/CD95, truncated BID (t-BID), apoptosis-inducing factor (AIF), and sequential activation of caspase-8, caspase-9, and caspase-3." (PMID 25072848, 2014). "Moreover, higher dosages of CuE (0.5–1 μM) induced the up-regulation of Fas/CD95, truncated BID (t-BID), AIF, and sequential activation of caspase-8, caspase-9, and caspase-3 in T24 bladder cancer cells." (PMID 25072848, 2014).
Cerebral ischemia (3 papers, 2016 to 2023). Restriction of arterial blood supply to the brain associated with insufficient oxygenation to support the metabolic requirements of the tissue. "In the intrinsic apoptotic pathway, cerebral ischemia elevates cytosolic calcium levels, which will activate calpains and mediate cleavage of Bcl‐2 interacting domain (BID) to truncated BID (tBID)." (PMID 37327371, 2023). "Inhibition of cysteine cathepsin B and L in astrocytes was reported to contribute to neuroprotection against cerebral ischemia via blocking the t-BID-mitochondrial apoptotic pathway." (PMID 35806122, 2022). "As BID is acting upstream of BAX in cell death signaling, these results indicate that other upstream, proapoptotic BH3-domain containing BCL-2 family proteins (“BH3-only proteins”) such as BIM and PUMA may play a more predominant role in BAX activation after cerebral ischemia." (PMID 26869884, 2016).
colitis (3 papers, 2018 to 2025). Inflammation of the colon. "Although few associations between BID and cancer have been investigated, evaluations of BID in human colorectal diseases, such as colorectal adenoma or colitis, have been demonstrated, suggesting that BID may be a possible mediator of CRC." (PMID 31578316, 2019). "We used the DSS-induced colitis model in mice to investigate the role of BID in development and resolution of colitis." (PMID 29495595, 2018). "To investigate the role of BID in development and resolution of acute colitis mediated predominantly by neutrophils and macrophages, we added 3% DSS to the drinking water for five days." (PMID 29495595, 2018). "Generation of conditional transgenic mice, such as for example a neutrophil-specific Bid-deficient strain, would allow definitive conclusions about the specific role of BID in neutrophils in DSS-induced colitis." (PMID 29495595, 2018). "Notably, knockout studies of BID and TLR8 in mice resulted in increased colitis and intestinal inflammation, supporting their association with decreased local inflammation as suggested by our IPA analysis." (PMID 40255128, 2025). "Overall, our results implicate that BID importantly regulates neutrophil death in the context of FASL > FAS and DSS colitis and that through this anti-inflammatory function BID may counteract development of inflammatory diseases such as IBD." (PMID 29495595, 2018).
diabetes (3 papers, 2016 to 2022). "Levels of pro-apoptotic proteins did not change in any IRS2−/− group regardless of diabetes: BAD (ND: 101%; D: 99% of WT values), truncated BID (t-BID)/BID (ND: 96%; D: 101% of WT values) and BIM (ND: 96%; D: 112% of WT values)." (PMID 27013528, 2016).
glioblastoma (3 papers, 2022 to 2025). The most malignant astrocytic tumor (WHO grade IV). "These proteins cleaved and activated BID to induce glioblastoma cells apoptosis." (PMID 34799992, 2022).
lymphoma (3 papers, 2021 to 2023). A malignant (clonal) proliferation of B- lymphocytes or T- lymphocytes which involves the lymph nodes, bone marrow and/or extranodal sites. "In these lymphoma cells, high levels of O-GlcNAc and Bortezomib lead to the accumulation of truncated BH3 Interacting Domain Death Agonist (Bid), a pro-apoptotic protein of the Bcl2 family, the level of which is further increased by direct O-GlcNAcylation, and ultimately results in apoptosis." (PMID 37838167, 2023). "Interestingly, loss of BID, together with FADD (Fas associated via death domain) and TRAIL (tumor necrosis factor-related apoptosis-inducing ligand), was reported to contribute to resistance of lymphoma cells to CD19 CAR T-cells." (PMID 34868059, 2021).
Myeloma (3 papers, 2022 to 2023). "Defect in the death receptor signally caused by impaired FADD/BID expression leads to failure of T-cell mediated immunotherapy in multiple myeloma patients." (PMID 38129580, 2023). "Myeloma cell death was associated with dual PI and Annexin-V positivity and increased expression of apoptotic genes, including CASP1, CASP8, CASP9, BAX, BID, and FASL." (PMID 36992311, 2023).
osteosarcoma (3 papers, 2020 to 2024). A usually aggressive malignant bone-forming mesenchymal neoplasm, predominantly affecting adolescents and young adults.
Salmonella Infections (3 papers, 2020 to 2023). Infections with bacteria of the genus SALMONELLA. "We also noted in these experiments that Casp1–/–;Casp11–/–;Casp12–/– iBMDMs showed more prominent processing of caspase-8 following Salmonella infection compared to WT iBMDMs and that this was accompanied by classical markers of apoptosis, such as cleavage of BID and caspases-3, -7, and -9." (PMID 32735843, 2020).
Alzheimer disease (2 papers, 2016 to 2017). A progressive, neurodegenerative disease characterized by loss of function and death of nerve cells in several areas of the brain leading to loss of cognitive function such as memory and language. "We have also analysed the interaction between BAX and BID, providing molecular evidence on the inverse comorbidity between cancer and Alzheimer’s diseases by means of changes in the pathways associated with apoptosis." (PMID 28740175, 2017).
bipolar disorder (2 papers, 2012 to 2026). A disorder of the brain that causes unusual shifts in mood, energy, activity levels and the ability to carry out day-to-day tasks. "The increased levels of the anti-apoptotic/pro–cell survival markers MCL1 and BCL2 and unchanged levels of the pro–cell death markers BID and BAX suggest a balance toward activated cell survival mechanisms in the midbrains of individuals with schizophrenia and bipolar disorder." (PMID 41567988, 2026). "Decreased BID transcript levels in the DLPFC were also observed in patient with bipolar disorder and thus not specific to just one psychotic disorder." (PMID 22545112, 2012).
breast tumors (2 papers, 2012 to 2021). "However, only the ECs of cGAMP-treated implanted breast tumours exhibited high expression of pro-apoptotic genes, including CASP3, CASP8, APF1, BID, BAX, and BAK." (PMID 34285232, 2021). "Additionally, a number of prosurvival (BCL2, PPEF2) and proapoptosis (BID, HEBP2, and PKNOX1) genes were up- and downregulated, respectively, in bone metastases compared with primary breast tumors." (PMID 23174366, 2012).
epilepsy (2 papers, 2016 to 2025). A brain disorder characterized by episodes of abnormally increased neuronal discharge resulting in transient episodes of sensory or motor neurological dysfunction, or psychic dysfunction. "In the study of neuronal apoptosis caused by epilepsy, researchers found that status epilepticus triggers BID activation, conversion to tBID, and subsequent translocation into mitochondria." (PMID 40093739, 2025).
hepatocellular carcinoma (2 papers, 2014 to 2024). A malignant tumor that arises from hepatocytes. "It has been shown that BID promotes intrinsic apoptotic pathway in hepatocellular carcinoma cells (HCC) because they are sensitized to etoposide by overexpression of BID." (PMID 25326334, 2014).
ischemia (2 papers, 2016 to 2017). A hypoperfusion of the BLOOD through an organ or tissue caused by a PATHOLOGIC CONSTRICTION or obstruction of its BLOOD VESSELS, or an absence of BLOOD CIRCULATION. "We also examined the effect of BID deficiency on the inflammatory responses to focal ischemia in vivo." (PMID 26869884, 2016).
renal carcinoma (2 papers, 2021 to 2024). A carcinoma arising from the epithelium of the renal parenchyma or the renal pelvis. "VCAN knockdown significantly reduced the proliferation of renal cancer cells and increased apoptosis, which is linked to the changes of several TNF signaling related genes such as TNFα, BID and BAK." (PMID 33836688, 2021). "Intriguingly, despite the expressions of BID, CDKN3, and PLK1 being consistently higher in the renal carcinoma cell lines than in the normal renal cells across both the primary and tenth passages, shifts in the gene expression levels among the carcinoma lines were noted." (PMID 38953023, 2024).
schizophrenia (2 papers, 2012 to 2026). A major psychotic disorder characterized by abnormalities in the perception or expression of reality. "However, as predicted by the results in the SMRI array database we found decreased transcripts levels of the pro-apoptotic BID in patients with schizophrenia." (PMID 22545112, 2012). "We found that smoking might interact with disease-specific factors in the schizophrenia group and contribute to decreased BID expression, a phenomena described previously for other transcripts." (PMID 22545112, 2012). "Conversely, other TNFSF downstream mRNAs were unchanged (BAX, BID, CASP1, CASP3, CASP8, and CASP9) in high-inflammation schizophrenia cases compared with low-inflammation controls." (PMID 41567988, 2026).
Stroke (2 papers, 2016 to 2024). Sudden impairment of blood flow to a part of the brain due to occlusion or rupture of an artery to the brain. "BID may still be an interesting subject in the stroke context, as we here show that BID modulates the inflammatory response to tMCAO." (PMID 26869884, 2016).
thyroid (2 papers, 2014 to 2024). "To investigate whether BID can cooperate with other thyroiditis risk factors to facilitate the development of autoimmune thyroiditis, we treated mice with iodine, a known risk factor for thyroiditis." (PMID 24957380, 2014). "To gain further insight into the role of BID in thyroid carcinogenesis, we assessed its expression level across the TCGA-THCA cohort based on genetic and clinicopathologic characteristics." (PMID 38540271, 2024). "The aim of this study was to determine whether an increase in BID expression in thyroid can induce autoimmune thyroiditis." (PMID 24957380, 2014). "We tested whether the increased expression of pro-apoptotic BID in thyroid would induce autoimmune thyroiditis, both in the presence and absence of 0.3% iodine water." (PMID 24957380, 2014). "However, the overexpression of BID itself is not sufficient to initiate thyroiditis in CBA/J (H-2 k) mice." (PMID 24957380, 2014).
viral infection (2 papers, 2020 to 2025). "The ability of Wt1-5 infection to induce the expression of caspases 3 and 8 and pro-apoptotic proteins BAX, Bcl2, and BID suggest that virus infection, at least at late stages of the viral life cycle, leads to apoptotic cell death." (PMID 32722005, 2020).
atrial fibrillation (1 paper, 2018). A disorder characterized by an electrocardiographic finding of a supraventricular arrhythmia characterized by the replacement of consistent P waves by rapid oscillations or fibrillatory waves that vary in size, shape and timing and are accompanied by an irregular ventricular response. "In order to more precisely characterize the effect of decreased genetically determined BID expression on cardiac phenotypes, we additionally analyzed the recently available GWAS of atrial fibrillation (N > 1 million individuals)." (PMID 30281024, 2018).
autoimmune disease (1 paper, 2024). A disorder resulting from loss of function or tissue destruction of an organ or multiple organs, arising from humoral or cellular immune responses of the individual to their own tissue constituents. "Aberrations in BID expression or function have been implicated in various diseases, and BID’s clinical relevance extends to conditions such as cancer, neurodegenerative disorders, and autoimmune diseases." (PMID 38384969, 2024).